GAST (gastrin)
Diseases named in the same sentence as GAST in open-access papers (continued):
Sharing a sentence is not in itself a finding about the gene and the disease.
tumor (continued). "Gastrin-MNPs targeted tumor cells by recognizing overexpressed gastrin receptors (CCK2R) and inducing LMP through MILH." (PMID 35656308, 2022). "In vivo study revealed that the tumor growth in nude mice inoculated with gastrin-overexpressed cells was significantly faster than control cells." (PMID 34976177, 2022). "These antibodies can bind to gastrin peptides to prevent their interaction with the CCK-BRs on the surface of tumor cells." (PMID 34926305, 2021). "Since exogenously administered gastrin or endogenously produced gastrin from the cancer cells can activate the CCK-BR receptor resulting in cellular or tumor proliferation, strategies to interrupt the interaction of gastrin should inhibit growth." (PMID 34926305, 2021). "First scintigraphic visualization of tumor lesions in a patient with metastasised MTC using 131I-labeled gastrin was undertaken by Thomas Behr in 1998." (PMID 34830930, 2021). "The best model for studying this and showing that hormonal overstimulation alone is sufficient to induce neoplasia is related to the role of gastrin in ECL cell hyperplasia, dysplasia, and neoplasia." (PMID 34202596, 2021). "Peptides such as secretin, gastrin, bombesin, cholecystokinin, and vasoactive intestinal peptide are believed to promote the proliferation of tumor cells." (PMID 32056066, 2020). "GAST not only increases the size of gastrointestinal tumors but also inhibits goblet cell differentiation and tumor cell apoptosis." (PMID 33282942, 2020). "Majority of Pan-NETs were less or the same staining intensity of the corresponding normal pancreatic endocrine cells or gastrin cells in the duodenum due to autonomous, faster hormone secretion by the tumor cells than normal endocrine cells." (PMID 32020844, 2020). "Due to the positive results of G17DT achieved in multiple gastrin-sensitive tumor models, the same group further investigated the therapeutic effectiveness of G17DT in clinical trials." (PMID 32210918, 2020). "In any way, the ECL cell can proliferate and develop into neoplasia, and gastrin has a positive trophic effect on this cell through its gastrin receptor." (PMID 31108898, 2019). "Another physiologic role of gastrin involves regulating proliferation of gastric mucosal cells, which leads to investigations into its effects on stimulation of tumor cell growth." (PMID 30115027, 2018). "We then investigated and found that low blood gastrin was correlated with tumor sizes and poor prognosis of the GC patients." (PMID 29866191, 2018). "With a radionuclide chelator attached to the N-terminus of CCK or gastrin peptide analogs, a variety of reagents have been created for tumor imaging and radiotherapy, including CCK-8, gastrin 10, mini-gastrin, gastrin dimers, and cyclic gastrin analogs." (PMID 29865257, 2018). "We also treated the PGC PDX mice with cisplatin and the combination of gastrin and cisplatin, and examined the tumor volume and weight as well as miR-23a, miR-27a and miR-24 expression in the tumor tissues." (PMID 29866191, 2018). "The results showed that treatment with both gastrin and cisplatin resulted in decreases in the tumor size and tumor weight, increases in miR-23a, miR-27a and miR-24 levels, compared with treatment with cisplatin alone." (PMID 29866191, 2018). "Several studies have shown that gastrin promotes tumor growth based on clinical observation or animal models of hypergastrinemia." (PMID 29866191, 2018). "The clinical presentation of functioning tumours depends on the peptide hormone being secreted such as insulin, gastrin, glucagon, vasoactive intestinal peptide (VIP) and somatostatin." (PMID 31447997, 2018). "Co-injection of the NEP inhibitor phosphoramidon with gastrin analogs increased their half-life in circulation and improved tumor uptake." (PMID 29865257, 2018). "This echoes with the clinical data showing that patients treated with curcumin demonstrated lower gastrin secretion, as well as decreased tumor burden." (PMID 28781948, 2017).
tumor (continued). "For this reason it is generally recommended that MEN1 screening be performed in all patients with ZES; in particular if the gastrin producing tumour is found in the duodenum." (PMID 28965289, 2017). "The lack of blood–brain barrier penetration is additional evidence that tumor targeting with a CCKBR AP offers significant advantages over gastrin targeting." (PMID 27754762, 2017). "Prolonged enterochromaffin cell exposure to gastrin can start a cascade of hyperplasia to neoplasia, with secondary tumors that have malignant potential." (PMID 25698559, 2015). "Some of these lesions are gastrin-sensitive, and some surgeons suggest testing the tumor itself for gastrin sensitivity as a treatment option." (PMID 25698559, 2015). "Wnt1 was detected in cells of the tumor stroma and its presence tended to decrease, as the level of gastrin in the tumor increased." (PMID 24901518, 2014). "Since the gastrin antibody used in this study recognizes both gastrin and gastrin precursors, like progastrin, we cannot discriminate between different gastrin peptides, but we observed extensive immunoreactivity in tumor epithelial cells of biopsies analyzed." (PMID 24901518, 2014). "Only a handful of studies have explored a potential role of gastrin signaling in tumor cell metastasis." (PMID 25346875, 2013). "Knock-down experiments with siRNA targeting NR4A2 increase migration of gastrin treated adenocarcinoma AGS-GR cells, while ectopically expressed NR4A2 increases apoptosis and hampers gastrin induced invasion, indicating a tumor suppressor function of NR4A2." (PMID 24086717, 2013). "We find that sustained expression of NR4A2 inhibits gastrin induced invasiveness, which is congruent with a tumor suppressor function of NR4A2 in AGS-GR cells." (PMID 24086717, 2013). "Another option is a somatostatin analogue, such as octreotide, which reduces tumour number and size, reduces serum gastrin concentrations indirectly, and reduces circulating chromogranin A (CgA), which is a marker of ECL-cell mass and activity." (PMID 24098507, 2013). "Gastric neuroendocrine tumours are currently classified according to their differentiation as well differentiated tumours, mainly composed by enterochromaffine-like cells or gastrin-producing cells." (PMID 24213225, 2012). "It would be interesting to investigate in future studies the potential role of gastrin in the mechanisms of metastasis of the tumor cells." (PMID 22719803, 2012). "Once the diagnosis has been biochemically established by fasting and stimulated gastrin concentration, localization and staging of the tumour are mandatory." (PMID 24213225, 2012). "In these nine cases with βHCG positive tumor cells, six cases were accompanied by gastrin, somatostatin and/or serotonin positive tumor cells." (PMID 20594358, 2010). "Some factors such as c-myc, cyclin D and gastrin reportedly relate to tumour proliferation, while others are related to tumour invasion." (PMID 11953860, 2002). "Gastrin has long been recognized as a mitogenic factor that stimulates the growth of pre-existing tumours of GI origin." (PMID 12189559, 2002). "In the present study, the PCNA index was significantly increased in gastrin-treated tumours when compared with control." (PMID 12189559, 2002). "In mice bearing either tumour model, administration of RC-160 significantly decreased serum growth hormone and gastrin levels." (PMID 7947094, 1994). "Effects of this therapy were assessed using serum marker concentration, Ki67 and gastrin-immunoreactivity of the primary tumour." (PMID 2069853, 1991). "Two colorectal (HT29, LoVo) and one gastric (MKN45) human tumour cell lines were examined for their in vitro trophic response to human gastrin-17." (PMID 2713241, 1989). "Besides the normalization of chromogranin A, insulin, and gastrin concentrations, an objective tumor response occurred in 10% of the cases, SD in 80% of the cases, and PD in 10% of the cases." (PMID 39996718, 2025).
tumor (continued). "Only one tumor stained for gastrin alone; the remainder all had a plurihormonal profile." (PMID 40553402, 2025). "and Dysregulation of GAST has also been associated with the development of various types of cancers,Additionally, POMC expression may be associated with tumor malignancy." (PMID 40098956, 2025). "While their direct impact on gastrin levels remains unclear, tumor control may indirectly help reduce hormonal output in certain cases." (PMID 40647278, 2025). "At the last examination, 50% of the tumor cells expressed gastrin and 5% insulin." (PMID 39382626, 2024). "Because of the autocrine stimulation of CCK2R by PDAC-secreted gastrin, competition between tumor gastrin and the reversible antagonist proglumide also may explain the greater fibrotic inhibition achieved by receptor downregulation." (PMID 38790986, 2024). "However, the effects of gastrin on tumor cell invasion were relatively weak in the presence of the extracellular matrix." (PMID 38069171, 2023). "Twenty-five days later, the volume and weight of tumors surgically removed from mice were significantly increased in the gastrin-overexpressed group compared to the control group, and gastrin was highly expressed in tumor tissues of nude mice in the gastrin-overexpressed group." (PMID 34976177, 2022). "Current clinical guidelines recommend annual surveillance for tumours by biochemical analyses (e.g. calcium, fasting glucose and hormones such as insulin, gastrin and prolactin) and radiological examination including MRI (or CT) scans of the pancreas and pituitary." (PMID 35900839, 2022). "Moreover, we observed that gastrin overexpression significantly promoted tumor formation in nude mice." (PMID 34976177, 2022). "The biological behavior of gastrin analogs might require radionuclides with longer half-lives than that of gallium-68 to allow proper visualization of the tumor sites." (PMID 34830930, 2021). "This enables specific targeting of tumor cells using gastrin analogs, labeled with radioisotopes." (PMID 34830930, 2021). "In theory, an antral tumor of advanced stage could destroy the gastrin releasing antral G cells, giving lower serum gastrin levels in cancers with antral location." (PMID 33091962, 2021). "Gastrin-induced signaling through CCK2R promotes tumor cell proliferation." (PMID 32210918, 2020). "Under such circumstances, a continued gastrin drive could result in microscopic foci of ECL neoplasia that subsequently manifest as an overt GNET." (PMID 32703157, 2020). "Gastrin might stimulate the growth of human tumor cells likely through a receptor other than CCK1R and CCK2R." (PMID 32210918, 2020). "While a causal relationship between PPIs and neoplasia has not been established in humans, it remains advisable to avoid high serum gastrin values for prolonged periods." (PMID 31684070, 2019). "Importantly, low gastrin level was correlated to clinicopathological characters involving ER subtype and tumor size." (PMID 30115027, 2018). "Gastroscopy before endoscopic ultrasound showed some ulcers, so that the hypothesis of a gastrin-producing tumor was favored." (PMID 29958547, 2018). "Clinical trials with gastrin antagonists could improve prognoses in those with gastrin receptor positive tumours." (PMID 30567376, 2018). "The syndrome is frequently associated with functioning pancreatic NETs, which most commonly secrete gastrin, glucagon, insulin or pancreatic polypeptide; less frequently tumours which secrete vasoactive intestinal polypeptide or growth hormone releasing hormone." (PMID 28965289, 2017). "On immunohistochemical studies, the tumor cells were positive for gastrin." (PMID 26546053, 2015). "The mean tumor size was 7.3 mm, and the mean gastrin level at diagnosis was 352.0 pg/ml." (PMID 26077245, 2015). "The esophagus also possesses CCK2 receptors, to which gastrin can bind, and promotes tumor growth." (PMID 25698559, 2015).
tumor (continued). "Searching for mediators that could modulate the phenotype of macrophages into the tumor we studied the role of gastrin peptides on the expression of different macrophage markers in the biopsy samples." (PMID 24901518, 2014). "The antral tumor suppressive function of gastrin could be explained to some extent by its effect on stimulating acid secretion leading to inhibition of bacterial overgrowth." (PMID 24216700, 2013). "CCKBRs have also been identified on cells in the tumor microenvironment, opening the possibility that gastrin signaling in the stromal compartment could have importance in tumor progression and/or dissemination." (PMID 25346875, 2013). "As expected increased basal acid output, tumour location (pancreas > duodenum), tumour size (large > small) and extent (liver metastases > local disease) all were positively correlated to the basal gastrin concentration." (PMID 24213225, 2012). "It seemed gastrin played a more dominant role than CCK in stimulating tumor growth." (PMID 23077482, 2012). "In addition the number of patients with both duodenal and pancreatic gastrin secreting tumours, justifying pancreatico-duodenectomy, is probably rather low." (PMID 24213225, 2012). "Both patients’ tumours demonstrated positive staining for gastrin." (PMID 24213231, 2012). "In order to identify common growth factor-responsive genes, which may represent candidate genes of tumour growth regulation in general, we compared gene expression induced by gastrin, HGF, EGF and PACAP." (PMID 15846300, 2005). "Gastrin, pituitary and target gland axis hormones, blood and urine catecholamines and their metabolites, aldosterone-renin-angiotensin system, fasting blood glucose, insulin, C-peptide, complete blood count, liver and kidney function, urinalysis, and tumor markers were all normal." (PMID 39371924, 2024). "The goal of these experiments was to test the effectiveness of the siRNA-loaded nanoparticle in preventing metastases in a mouse with a heavy tumor burden and also to examine whether combination treatment with GAST siRNA and muKRAS siRNA NPs could be co-administered and enhance the efficacy." (PMID 36614194, 2023). "The action of somatostatin analogues, such as octreotide or lanreotide, which inhibit gastrin secretion and consequent enterochromaffin cell proliferation, provides a mechanism to block the hyperplasia and dysplasia that eventually leads to neoplasia, and could thus prevent the appearance of GC-1." (PMID 36979851, 2023). "However, the invasion of tumor cells stimulated by the presence of fibroblasts was increased further by treatment with gastrin (one-way ANOVA, ECM w/ fibroblasts and G17 vs. ECM w/o fibroblasts and G17, p < 0.001; ECM w/fibroblasts vs. ECM w/fibroblasts and hG17, p = 0.002)." (PMID 38069171, 2023). "Moreover, gastrin-driven gastric carcinogenesis shows that neoplasia including cancer may develop from differentiated cells with the ability to divide, as exemplified by the ECL cell." (PMID 34202596, 2021). "Moreover, it is likely that such information could be used to define the likelihood of a gastrin-induced ECL cell hyperplasia transforming into a neoplasia." (PMID 32703157, 2020). "Serotonin-secreting pNETs may originate as de-differentiated tumours with a mixed cellularity, showing a co-secretion of other substances/hormones (i.e., 5-HT, calcitonin, gastrin, substance P, neurokinins, etc.), or from pancreatic enterochromaffin cells well differentiated in 5-HT production." (PMID 32384679, 2020). "Finally, nanoparticles can be bioconjugated with gastrin peptide to improve tumor-specific uptake." (PMID 29865257, 2018). "Thus, we tested if gastrin could induce autophagy and if this could contribute to tumor progression." (PMID 28109268, 2017). "Furthermore, at which stage of tumor development gastrin loses its effect must be elucidated, in order to determine whether a gastrin antagonist could be used in the treatment." (PMID 28144230, 2017).
tumor (continued). "However, like most peptide targeting agents, the use of gastrin to direct cargo to tumor cells has been hampered by off-target binding, especially in the brain in the case of gastrin, as well as relatively high cost and serum instability/proteolytic degradation." (PMID 27754762, 2017). "However, plasma gastrin level normalized shortly after the excision of the tumor." (PMID 26546053, 2015). "Biochemical work-up may include 5-HIAA, gastrin, and other locally available tumor markers." (PMID 25038902, 2014). "In addition, there is abundant evidence to suggest that gastrin may play an important role in tumour biology, as it is shown to regulate tumour cell growth, and stimulate tumour cell invasion as well." (PMID 15846300, 2005). "Thus, a downregulation of IGFBP1 by gastrin may be one mechanism whereby gastrin promotes tumour growth and invasion." (PMID 15846300, 2005). "Tumour growth in the lansoprazole treated mice was greater than in the omeprazole treated mice, which may relate to the higher serum gastrin levels, and was completely reversed by co-administration of antiserum blockading the CCK-2 receptor, confirming the growth effect as gastrin-specific." (PMID 12189558, 2002). "In contrast, upregulated neuropeptides GAST and NMB correlated negatively with upregulated ICGs (p < 0.05), which is indicative of their potential role in anti-tumor immunomodulation." (PMID 40805163, 2025). "Strategies to disrupt the gastrin interaction have the potential to inhibit cancer cell growth since exogenous administration or endogenous production of gastrin from cancer cells can activate the CCK-BR receptor, leading to tumor proliferation." (PMID 39003350, 2024). "Positive labeling for chromogranin A was found in 21/22 neoplasms (95.45%), while 18/19 (94.74%) were positive for neuron-specific enolase (NSE), and 13/15 (86.67%) were positive for gastrin." (PMID 39195825, 2024). "Cultures of the primary tumor were positive for many neuroendocrine markers over several passages, including CgA, NSE, somatostatin, SSTRs, and gastrin, among others." (PMID 39649120, 2024). "The effect is mediated by gastrin/Cholecystokinin B2 receptor (CCKB2R) on the ECL cell membrane, which in turn leads to hyperplasia, dysplasia, and finally neoplasia." (PMID 38610738, 2024). "Its ligands, gastrin and cholecystokinin (CCK), drive increased tumor growth and are often aberrantly upregulated in PDAC cells." (PMID 38790986, 2024). "Gastrin transcript levels were evaluated in gastrin-expressing AGS, MKN-45G, and BON-1 tumor cell lines following transient overexpression of wild-type and menin mutant proteins." (PMID 37492626, 2023). "Studies have demonstrated the importance of both PAS monotherapy for cytokine release upon re-stimulation with gastrin and of PAS and PD-1 antibody combination therapy for T cell-mediated tumour death and memory." (PMID 37686543, 2023). "Compared with normal tissues, only SLURP1 was downregulated in tumor tissues, while the expression levels of DKK1, GAST, IGHM, IL12RB2, STC2, and TNFRSF4 were upregulated in tumor tissues." (PMID 39282247, 2023). "The tumorigenesis mechanism is mediated by the effects of gastrin on the CCK2R receptor in ECL cells, which leads to hyperplasia, dysplasia, and finally, neoplasia." (PMID 36979851, 2023). "IFI27, LCN2, GAST, and SERPINA1 were downregulated after NACT in tumor cells, while OLFM4, MRPS35, MMP1 and MED21 were upregulated in tumor cells." (PMID 36474268, 2022). "Exploration of the expression network indicated that inflammatory genes (CXCL8, CXCL3, PIGR, and RNASE1) and Wnt pathway genes (GAST, REG1A, TFF3, and ZG16B) are upregulated in tumor stem cells of UGICs." (PMID 35646860, 2022). "During gastrin-induced migration, Fas-induced EMT and endothelin-1-mediated EMT and tumour invasion, the inactivation of GSK-3β by PI3k/Akt signalling promotes Snail expression and β-catenin stabilisation." (PMID 33239678, 2021).